LEF1 (lymphoid enhancer binding factor 1)
Diseases named in the same sentence as LEF1 in open-access papers (continued):
Sharing a sentence is not in itself a finding about the gene and the disease.
tumor (continued). "The different distribution of LEF-1 in tumor cells and peritumor cells suggests that different mechanisms could be involved in the pre-malignant stage and the malignant stage in HBV associated HCC." (PMID 19402906, 2009). "Compared to those in normal liver tissues, though both isoforms were significantly up-regulated in HCC, the 38 kDa truncated isoform of LEF-1 was more significantly up-regulated in tumor cells, than that in peritumor cells especially in those 13 HBsAg positive HCC tissues." (PMID 19402906, 2009). "This could partly be attributed to the over-expression of 38 kDa dominant negative LEF-1 isoform in tumor cells." (PMID 19402906, 2009). "Interestingly, the intracellular distribution of LEF-1 protein in tumor cells was different from that in peritumor cells." (PMID 19402906, 2009). "In contrast to other tumours, the transcriptional activity of Lef-1/β-catenin might play a minor role in ovarian epithelial tumours." (PMID 14520463, 2003). "However, this study did not investigate the tumor growth potential associated with LEF1 expression in fibroblasts." (PMID 39887653, 2025). "In summary, our findings suggest that LEF1 expression contributes to the tumor‐promoting abilities of breast CAFs and that LEF1‐expressing CAFs may drive transdifferentiation toward SCC, possibly through a pathway independent of the canonical Wnt/β‐catenin signaling." (PMID 39887653, 2025). "Moreover, isolated islets of LEF1+ cells were observed predominantly in post-chemo tumor tissues." (PMID 39567475, 2024). "Indeed, low PDZK1 expression also correlated with LEF1 hyperactivity in this tumor type." (PMID 37225693, 2023). "The nuclear β-catenin along with lymphoid enhancer binding factor 1 (LEF-1) activates FUT8 expression, causing FUT8 upregulation, globally altering core fucosylation, cancer cells’ response to extracellular matrix, growth factors, and other elements of the tumour microenvironment." (PMID 33466384, 2021). "Finally, we used 18 paired CRC patient specimens in the CRC tissue array to demonstrate that the expression of FoxO1 in the nuclei was significantly lower in tumor specimen and the miR-449a target genes LEF-1 was highly expressed in the tumor parts compared to the non-tumor parts." (PMID 34737955, 2021). "Additionally, LEF1 IHC was performed in representative whole slides of 21 tumours." (PMID 34420090, 2021). "Furthermore, LEF1 can induce myodifferentiation of the tumor cells." (PMID 27965462, 2017). "However, the fact that LEF1 fosters invasiveness of Rh41 cells indicates that this tumor suppressive function may be restrained to specific RMS subgroups." (PMID 27965462, 2017). "Over-expression of Smad4 rescued the NB cells from LEF1-facilitated growth, invasion and angiogenesis, suggesting that Smad4 may exert its tumor suppressive functions, at least in part, through interacting and repressing the LEF1 activity in regulation of HPSE expression in NB." (PMID 27595937, 2016). "Furthermore, among the significantly upregulated genes in the TGF-β signaling pathway, lymphoid-enhancing factor 1 (LEF1) was of particular interest, as it is known to have a functional role in the Wnt/β-catenin pathway, another important pathway for tumor growth and invasion." (PMID 25120605, 2014). "Moreover, the high Lef1 levels in the tumor cells appeared not to be a result of the deregulated Notch signaling, as inhibition of the Tcf1−/− tumor cells by DAPT only mildly affects Lef1 levels, whilst both Notch target genes Hes1 and Deltex were completely down-regulated." (PMID 23185135, 2012). "Therefore LEF-1 expression might indicate an activated TGFβ signalling which reduces tumour progression and development of metastasis." (PMID 21092222, 2010). "Specifically, VDR downregulates the expression of β-catenin, cyclin D1 and LEF-1 in vitro, and xenografts established by VDR-overexpressing SW480 cells shows suppression of tumor growth and decreased expression of β-catenin, cyclin D1 and LEF-1." (PMID 40630116, 2025).
tumor (continued). "It is worth noting that vIRF1 can interact with lymphoid enhancer binding factor 1 (Lef1), activate circARFGEF1 transcription and regulate cell migration through the circARFGEF1/miR-125a-3p/glutaredoxin 3 (GLRX3) axis, contributing to tumor development." (PMID 40182764, 2025). "In vivo, CAFs promoted CRPC tumor growth and significantly increased the expression of Wnt3a, β-catenin, TCF4, LEF1, SDF-1, and CXCR4, along with an elevated p-GSK-3β/GSK-3β ratio." (PMID 40735647, 2025). "Altogether, these results suggest that LEF1 regulates genes unrelated to the canonical Wnt/β‐catenin signaling in exp‐CAF 544 cells and plays a role in mediating their tumor‐promoting ability." (PMID 39887653, 2025). "When dividing the cohort according to median LEF-1 expression, we found significantly down-regulated expression of 37 genes in LEF-1high-expressing tumours." (PMID 40130164, 2025). "However, while we observed a direct association between CTNNB1 and CD3+ immune cells, LEF-1 was not linked to any of the immune cell subtypes but interestingly associated with impaired expression of antigen presentation in tumours suggesting modulation of immune recognition." (PMID 40130164, 2025). "The embryonal HBTOs were enriched with WNT target genes and EMT markers, including AXIN2, LEF1, DKK1, NOTUM, NKD1 and VIM, in line with the embryonal tumor signature." (PMID 39567475, 2024). "We performed gene regulatory network analysis on this dataset and identified enrichment of WNT pathway regulons, specifically LEF1 and TCF7, in the embryonal tumor organoids, while HNF4A was enriched in the fetal-I and II tumor organoids." (PMID 39567475, 2024). "LEF1 and RUNX2 were identified as highly active transcription factors in the calcification subtype of tumor cells." (PMID 39483146, 2024). "The tumor and development-process marker genes LEF1 and PHF20 have a tendency to change depending on storage time, which will affect the accuracy of correct tumor-marker screening or early screening." (PMID 38674435, 2024). "This group was enriched in key WNT pathway TFs, such as LEF1, TCF7, and TCF7L2, which was corroborated by the chromatin accessibility landscape analysis of a cohort of tumor organoids established in this study." (PMID 39567475, 2024). "Many of the DEGs were involved in ferroptosis (Ptgs2), enhanced T-cell function (Lef1), regulators of EMT (Zeb1, Zeb2, Vimentin, and Sfrp2), and fibrosis (Col1α1 and Acta2) in the tumor microenvironment." (PMID 36835036, 2023). "Our results showed that LEF1 recruits KDM4A and N-CoR, functioning in a coordinated manner to transcriptionally inhibit the tumour-suppressor gene LATS2 and promote OSCC progression." (PMID 37553362, 2023). "The results further confirmed that LEF1 and KDM4A were notably upregulated in tumours and that the differential expression of LEF1 and KDM4A was related to OSCC histological grade." (PMID 37553362, 2023). "The expression of the indicated proteins in tumour specimens was analysed by WB, revealing higher LATS2 expression in the LEF1- or KDM4A-knockdown groups." (PMID 37553362, 2023). "Selenite treatment inhibits LEF1 recruitment to the CYLD promoter and reduces the average tumour weight in colorectal cancer." (PMID 37553362, 2023). "Comparing the expression in the normal epithelium and tumour tissues from histological grade I, II, III, or IV revealed that higher histological grades corresponded to higher LEF1 and KDM4A mRNA expression." (PMID 37553362, 2023). "Cells stably suppressing LEF1 or KDM4A had markedly decreased tumour-initiating capacity, with tumours from the control shRNA (shSCR) group notably larger than those from the other two groups." (PMID 37553362, 2023). "We also detected the expression of key genes involved in Wnt/β-catenin signalling (β-catenin, lymphoid enhancer factor (LEF)-1 and cyclin D1) in SW480 cells and nude mice injected with VDR-overexpressing SW480 cells and observed tumour development." (PMID 37046222, 2023).
tumor (continued). "RNA-sequencing (RNA-seq) analysis of 566 samples (44 normal and 522 tumour) suggested that LEF1, KDM4A, and KDM4D were expressed at higher levels in tumour tissues than in normal tissues, whereas KDM4B was expressed at lower levels in tumour tissues." (PMID 37553362, 2023). "On the other hand, CTNNB1 knockdown inhibits the Wnt/β-catenin signaling pathway and downregulates the expression of downstream genes, including axin 2, lymphoid enhancer-binding factor 1 (LEF1), and cyclin D1, thereby inhibiting tumor proliferation." (PMID 37033970, 2023). "Lef1 mRNA is elevated in multiple mouse models that develop T-ALL, and as described later in this review, LEF1 can play both oncogenic and tumor suppressor roles in these models depending on the timing of its expression." (PMID 35514954, 2022). "The tumor cells were positive for arginase-1, CD10 (with canalicular enhancement), CD56, cytokeratin 8/18/19, Hep Par-1, β-catenin, LEF1, and androgen receptor (weak positivity)." (PMID 35359182, 2022). "Additionally, we aimed to analyse the potential correlation of LEF1 and beta-catenin IHC with CTNNB1 exon 3 hotspot mutation, and to identify morphological parameters that could be predictive of CTNNB1 mutation in these tumours." (PMID 34420090, 2021). "Results showed that the relative expression of LEF1, VLDLR, RARRES2 and TNFRSF10C were significantly up-regulated compared to adjacent non-tumor tissues and other metastatic sites (P < 0.05)." (PMID 34256750, 2021). "Remarkably, these pairwise comparisons also reveal that any link to extracellular matrix (ECM) generally excludes TCF7 and TCF7L2, but generally includes both TCF7L1 and LEF1; TCF7L1 more in normal tissue, and LEF1 more in tumor." (PMID 32403323, 2020). "Cell adhesion-associated gene expression is correlated with TCF7L2 expression specifically in normal tissue, and with LEF1 and TCF7L1 in tumor tissue." (PMID 32403323, 2020). "Our previous study reported that LEF1 was predominantly expressed in ESCC cell lines and tumor tissues and that the positive expression of LEF1 was correlated with aberrant clinicopathological characteristics in ESCC patients." (PMID 32226522, 2020). "In mice, the epithelial expression of TCF4 is indispensable for cell proliferation and tumor initiation but in humans, the TCF4 role is redundant with the related TCF1 and LEF1 transcription factors." (PMID 32053894, 2020). "Tumor tissues were then divided into groups with high and low levels of IRF3, TCF1, and LEF1 according to IHC scores." (PMID 33188184, 2020). "Our meta-analysis confirms that among the four human LEF/TCF genes, LEF1 and TCF7 are preferentially expressed in tumor biopsies, while TCF7L2 and TCF7L1 in normal control tissue." (PMID 32403323, 2020). "In this study, we found that the overexpression of LEF1 promoted the stem cell-like properties of CSCs in ESCC, including spherical tumor formation, chemoresistance, and tumorigenicity." (PMID 31296250, 2019). "Based on their tumor LEF1 and OV6 content, the patients were classified into 4 groups: group A, high OV6 and LEF1 intensity; group B, high OV6 but low LEF1 intensity; group C, high LEF1 but low OV6 intensity; and group D, low OV6 and LEF1 intensity." (PMID 31296250, 2019). "Our previous studies reported that LEF1 is predominantly expressed in ESCC cell lines and tumor tissues and that the positive expression of LEF1 is correlated with aberrant clinicopathological characteristics of ESCC patients." (PMID 31296250, 2019). "Further DY131 treatment of xenograft tumor samples led to decreased expression of Ki67, the three Wnt components (TCF4, LEF1, and β-catenin), and the CCND1 Wnt downstream target gene." (PMID 29765046, 2018). "BMI1, as well as other tumor promoting genes (like EGFR and LEF1) were significantly upregulated in NCH644 in contrast to our expectations (adjusted p-values calculated by DESeq2, · = p < 0.1, * = p < 0.05, ** = p < 0.01, *** = p < 0.0001)." (PMID 29724193, 2018).
tumor (continued). "The involvement of Wnt signaling pathway, including LEF1 and TCF7L2, in the promotion of invasion, CSC self-renewal, and metastasis of TNBC as well as other tumor types (i.e., lung and prostate) had been established." (PMID 29179446, 2017). "Conversely, LEF1 can repress the transcription of MYC and thus act as a tumor suppressor in a subset of human T-ALL cases." (PMID 27965462, 2017). "It has been reported that DNA methylation of SMAD4, LEF1, and CCR7 demonstrate varying expression levels (p < 0.05) between tumor and normal samples (MethHC database), which support our results." (PMID 26895224, 2016). "TCF7L1 expression was upregulated in lines derived from metastatic tumours compared to primary tumours, while conversely both TCF7L2 and LEF1 were strongly downregulated in the metastatic lines." (PMID 27531891, 2016). "HCCs with microscopic vascular invasion had high mRNA levels of HAPLN1, LGR5, LEF1, SOX9, CD44, Glypican 3 and larger tumor size." (PMID 27191501, 2016). "We next tested the cytotoxicity of EA in different tumor cell lines, and in primary CLL cells that are known to have constitutive Wnt activation and very high levels of LEF-1." (PMID 20011538, 2009). "The distribution of cellular LEF-1 in peritumor tissues was predominantly in the cytoplasm; while LEF-1 in the tumor tissues was located either exclusively in the nucleus or both in the nucleus and cytoplasm." (PMID 19402906, 2009). "These genes are known to be involved in tumour cell proliferation and invasion via activation of the transcription factor TCF/LEF1." (PMID 17233884, 2007). "Instead, Snail's tumor-promoting activity is largely mediated through its cooperation with EGR1/SP1 transcription factors on non-canonical TCACA promoter elements, which upregulate genes such as ZEB1, MMP9, and LEF1." (PMID 42152116, 2026). "Consequently, high LEF1 expression enables CRC cells to resist the inhibitory effects of TGF-β signaling, further promoting EMT and enhancing tumor invasiveness and metastasis." (PMID 40810004, 2025). "Within the intricate tumor microenvironment, when perturbations arise in cell-cell interactions and purine metabolic processes, the expression profiles and functional activities of CTNNB1 and LEF1 are prone to undergo alterations." (PMID 40236698, 2025). "In the current study, however, LEF1 depletion in 544 cells did not decrease mRNA expression of CXCL12 and TGF‐β, suggesting they are not involved in LEF1‐medicated tumor‐promoting effect of 544 cells." (PMID 39887653, 2025). "For comparison, 6 tumours had a high number of CD3+ T cells/HPF and intermediate LEF-1 expression." (PMID 40130164, 2025). "Patients categorized as negative for β-catenin displayed cytoplasmic or membranous staining in approximately 20–40% of tumor cells, with two patients showing no β-catenin immunoreactivity yet exhibiting approximately 30% LEF1 nuclear expression." (PMID 39881334, 2025). "Conversely, the embryonal tumor organoids showed LEF1 expression broadly, with HNF4A largely absent." (PMID 39567475, 2024). "Further, IHC for LEF1 was done on the tumor in the appendix, and it was found to be negative, thus, ruling out small lymphocytic lymphoma (SLL)." (PMID 39328717, 2024). "This assumption is fostered by finding significantly lower expression levels of TCF4, whereas TCF4 is known to be in a direct interaction with LEF1 known as an interaction TCF/LEF, where overexpressed LEF1 leads to an enhanced tumor cell invasiveness and induces epithelial to mesenchymal transition." (PMID 38003292, 2023). "Besides being significantly correlated with tumor recurrences and metastases, the FUT8 increase seemed to be triggered by β-catenin/lymphoid enhancer-binding factor-1 (LEF-1) signaling." (PMID 36980181, 2023).
tumor (continued). "We also established NOD/SCID mouse xenograft models using CAL-27 cells to conduct an in vivo analysis of the roles of LEF1 and KDM4A in tumour growth, and our findings show that cells stably suppressing LEF1 or KDM4A have markedly decreased tumour-initiating capacity." (PMID 37553362, 2023). "In the PDTX model, administration of SR3029 obviously delayed tumor growth, concomitant with an increased protein level of AES and a decreased expression of Wnt target genes (Axin2, Fibronectin and LEF1), stemness marker genes (CD44 and LGR5) and Notch target genes (HES1 and HES2)." (PMID 33754069, 2021). "As a result, several hub DEFs with maximum intramodular connectivity were identified (e.g., SOX4, EGR1, LEF1, FOS, MITF, KLF4, TCF7, and KDM6B), which might involve CD248-mediated tumor-promoting regulation in CAFs." (PMID 34970489, 2021). "At this time point, EdU incorporation and cleaved Casp3 staining indicated that Lef1 deletion increases tumor cell proliferation, but not apoptosis." (PMID 34788095, 2021). "By treating mice with positively charged polyethylenimine (PEI)‐condensed DNA oligo‐based O'PROTAC, we demonstrated that LEF1 OP‐V1 effectively inhibited PC‐3 and DU145 tumor growth in mice compared to the treatment of phosphate‐buffered saline (PBS) or control OP." (PMID 34397171, 2021). "LEF-1 cross-talks between HGF/c-Met and Wnt/β-catenin to coordinate tumor migration and invasion." (PMID 34737955, 2021). "Furthermore, SMOM2 induced upregulation of Wnt/β-catenin signaling, as shown by increased nuclear β-catenin and lymphoid enhancer-binding factor-1 (LEF1) expression, which led to mice BCC and human BCC tumor initiation." (PMID 34572373, 2021). "LEF1, which is a member of the LEF/TCF complex, may act as either a tumor suppressor or an oncogene in different cellular contexts." (PMID 32046053, 2020). "Positive correlations linking TCF7 with LEF1 and with LGR5 in normal tissue are reduced in tumor tissue, and the negative correlation between AXIN2 and TCF7L1 in normal tissue is also reduced in tumor tissue." (PMID 32403323, 2020). "Our meta-analysis of transcriptomics studies provides a clear picture of altered LEF/TCF gene expression, confirming TCF7L2 in normal and LEF1 expression in tumor tissue, but also higher than expected TCF7L1 in normal and relatively higher TCF7 expression in tumor tissue." (PMID 32403323, 2020). "LEF1 activates β-catenin/TCF4 transcriptional activity, promoting tumor growth and progression." (PMID 32933177, 2020). "Among the genes regulated by LEF1, some demonstrated increased expression in tumor compared with non-tumor tissue, whereas others showed decreased expression." (PMID 32854182, 2020). "We first tested our hypothesis about differential expression of LEF/TCF genes between tumor and normal tissue with forest plots of all four LEF/TCF genes (TCF7, LEF1, TCF7L1, TCF7L2)." (PMID 32403323, 2020). "LEF1 expression was significantly different between tumor and non-tumor tissue (p = 0.0405) with higher expression seen in tumor compared with non-tumor tissue." (PMID 32854182, 2020). "Another way in which the miR-34 family contributes to tumour suppressive function is that miR-34a, miR-34b*, and miR-34c-5p inhibit the Wnt pathway by repression of Wnt ligand co-receptors (WNT1/3; LRP6), with HMG-box transcription factor (LEF1) and β-catenin." (PMID 31658284, 2019). "Our findings of high expression of Cyclin D1 and significantly higher expression of AXIN2, LEF1 and ZNRF3 mRNA in tumours harbouring the ∆(2 + 3) deletion at a similar level to those with hot spot mutations suggest the activating nature of these deleterious mutations in ACCs." (PMID 29872083, 2018). "Considering that LEF1 is reportedly involved in cell EMT, invasion, and migration, it was necessary to investigate whether the effects of OCT4 on tumor EMT, invasion, and migration are mediated by LEF1 in the Eca109 cell line." (PMID 29974668, 2018).